SCLT1 (sodium channel and clathrin linker 1)
Description:
Adapter protein that links SCN10A to clathrin. Regulates SCN10A channel activity, possibly by promoting channel internalization (By similarity).
Synonyms: hCAP-1A; FLJ30655; CAP-1A; CAP1A
Tractability: PROTAC: ubiquitination databases record sites on it.
Gene: Protein-coding gene on chromosome 4 (128,864,921 to 129,093,600, reverse strand). Ensembl gene ENSG00000151466.
Subcellular location: Cytoplasm, cytoskeleton, microtubule organizing center, centrosome, centriole
Subcellular location (Human Protein Atlas): Basal body; Cytosol; Microtubules
Pathways (Reactome):
Organelle biogenesis and maintenance: Anchoring of the basal body to the plasma membrane
Gene Ontology:
Molecular function: clathrin binding; sodium channel regulator activity
Biological process: cilium assembly; clustering of voltage-gated sodium channels
Cellular component: centriole; centrosome; ciliary basal body; ciliary transition fiber; cytosol; clathrin complex
Genetic constraint (gnomAD): Loss-of-function variants: 11 observed, 16.57 expected, observed/expected ratio (o/e) 0.66, 90% interval 0.42 to 1.1. The upper end of that interval is the gene's LOEUF score, 1.1, which puts it in group 4 of 6, group 1 being the genes least tolerant of losing a copy. Missense variants: 137 observed, 150.95 expected, observed/expected ratio (o/e) 0.91, 90% interval 0.79 to 1.05. Synonymous variants: 55 observed, 53.46 expected, observed/expected ratio (o/e) 1.03, 90% interval 0.83 to 1.29.
Homologues: Orthologues: chimpanzee SCLT1 (99% identical), macaque SCLT1 (88% identical), dog SCLT1 (84% identical), rabbit SCLT1 (84% identical), guinea pig SCLT1 (81% identical), pig SCLT1 (81% identical), rat Sclt1 (76% identical), mouse Sclt1 (75% identical), tropical clawed frog sclt1 (55% identical), zebrafish sclt1 (49% identical).
Diseases named in the same sentence as SCLT1 in open-access papers:
SCLT1 is named in the same sentence as 20 diseases in open-access papers, as found by Europe PMC text mining. Sharing a sentence is not in itself a finding about the gene and the disease. The quoted sentences say what the papers report.
ciliopathy (6 papers, 2016 to 2025). A genetic disorder of the cellular cilia or the cilia anchoring structures, the basal bodies, or of ciliary function. "In humans, mutation of SCLT1 causes ciliopathies and is subcategorized as an oral-facial-digital syndrome." (PMID 36407107, 2022). "Mutations in three genes encoding DAP proteins, namely, CEP83, CEP164, and SCLT1, have been reported to be linked to heritable ciliopathies, such as NPHP and Joubert syndromes." (PMID 34830133, 2021). "In conclusion, we identified compound heterozygous splice site variants of SCLT1 in a patient with a new form of ciliopathies that exhibits clinical features of SLS." (PMID 30425282, 2018). "However, it also provides the some aspect of conserved role for Sclt1 as in human mutation which causes a ciliopathy and phenotypic features ranging from cleft palate to coloboma." (PMID 36407107, 2022). "CFAP45 and PROM1 are found in both atypical and secondary ciliopathies, whereas TTC26, SCLT1, DNAJB11, DYNC2LI1, ALMS1, IFT80 and IFT74 are shared between primary and atypical ciliopathies." (PMID 37542408, 2023).
cystic kidney (2 papers, 2018 to 2022). "A recent study from transgenic insertion allele for Sclt1 found that loss of Sclt1 causes cleft palate, cystic kidney, and polydactyly." (PMID 36407107, 2022). "The Sclt1tm1a embryo showed the formation of a shortened intestine, cystic kidney, and cleft palate which are consistent with previous study from intragenic insertional allele of Sclt1." (PMID 36407107, 2022).
cystic kidney disease (2 papers, 2018 to 2020). A congenital or acquired kidney disorder characterized by the presence of renal cysts. "SCLT1 deficiency has been linked with cystic kidney disease, and SMAD genes (including SMAD3) have been reported to affect CKD progression when they are dysregulated." (PMID 32386536, 2020).
microcephaly (2 papers, 2022). A congenital or acquired developmental disorder in which the circumference of the head is smaller than normal for the person's age and sex. "Recently, human mutation of SCLT1 has been known to cause oral-facial-digital syndrome type IX in which defects are manifested as in a midline cleft of palate, microcephaly, and coloboma." (PMID 36407107, 2022). "KIF14 mutations can also lead to microcephaly and have been shown to disturb PC formation and disrupt the localisation of the DAPs SCLT1 and FBF1 as well as components of the IFT-B complex." (PMID 36139475, 2022). "SCLT1, and TBC1D32 a TZ protein, are both required for initiating ciliogenesis, with mutations giving rise to severe ciliopathies (OFD type IX) including microcephaly." (PMID 36139475, 2022).
chronic renal failure (1 paper, 2020). "The Sclt1 (sodium channel and clathrin linker 1) has been found to be associated with nephronophthisis, the most frequent genetic cause of chronic renal failure in children." (PMID 32175184, 2020).
liver fibrosis (1 paper, 2020). "As such, in this study, we investigated the specific biological role of hsa_circ_0070963, which is transcribed from SCLT1 (Sodium channel and clathrin linker 1) on chromosome 4, in liver fibrosis." (PMID 32003753, 2020).
lung squamous cell carcinoma (1 paper, 2023). "Moreover, NEDD9, MRPL21, SNRPF, and SCLT1 genes were identified to be involved in lung squamous cell carcinoma drug sensitivity/resistance." (PMID 37185598, 2023).
Obesity (1 paper, 2022). Accumulation of substantial excess body fat. "Human mutations of SCLT1 cause variable clinical features such as obesity, defects in craniofacial development, eye, and kidney, and they are not overlapping for each other." (PMID 36407107, 2022).
orofaciodigital syndrome IX (1 paper, 2020). "These include CEP83 (mutations in CEP83 cause NPHP18), CEP89, SCLT1 (variants in SCLT1 may be associated with Orofaciodigital syndrome 9), and FBF1." (PMID 31990917, 2020).
autosomal recessive disease (1 paper, 2023). Autosomal recessive form of disease. "With our study, we provided Moderate or Strong level of evidence for GDR for 11 genes that were not listed in OMIM as having phenotype entity: FBRSL1, AGR2, ACBD6, C1orf127, PAN2, VPS50, KCTD3, NOTCH3 (for autosomal recessive disease), FAT1, NRAP, and SCLT1." (PMID 39669245, 2023).
cancer (1 paper, 2023). A tumor composed of atypical neoplastic, often pleomorphic cells that invade other tissues. "It has been reported that SCLT1 by inducing apoptosis combined with chemotherapy drugs enhanced cancer cell death." (PMID 37185598, 2023).
genetic disease (1 paper, 2024). "However, mutation in the human SCLT1 gene causing the genetic disease of oral-facial-digital (OFD) syndrome." (PMID 39502208, 2024).
SCLT1 also shares sentences with these, for which no sentence is quoted: Bardet-Biedl syndrome (1 paper); coloboma (1); Joubert syndrome (1); nephronophthisis (1); oral-facial-digital syndrome (1); polydactyly (1); retinal degeneration (1); Senior-Løken syndrome (1).